EGFR (epidermal growth factor receptor)
Diseases named in the same sentence as EGFR in open-access papers (continued):
Sharing a sentence is not in itself a finding about the gene and the disease.
cervical carcinoma (continued). "In this present study, we examined the effect of CD73 overexpression on EGFR and VEGF expression in cervical cancer cells." (PMID 28202050, 2017). "Further, we demonstrated a biological link among HPV16 E6, miR-2861, EGFR, AKT2, and CCND1 in cervical cancer cells." (PMID 27364926, 2016). "However, the value of using EGFR inhibition to treat cervical cancer remains unknown." (PMID 27438047, 2016). "The main objectives of the present study were to determine the effects of THC on tumor growth in cervical cancer- (CaSki-) implanted nude mice and to study the possible mechanisms of THC on EGFR and COX-2 expression and their signaling." (PMID 26881213, 2016). "In summary, we delineates a novel regulatory network employing HPV16 E6, miR-2861, and EGFR/AKT2/CCND1 signaling pathway to fine-tune proliferation, apoptosis, and invasion in cervical cancer cells." (PMID 27364926, 2016). "Meanwhile, overexpression of EGFR, AKT2, and CCND1 eliminate the effect of miR-2861 on cervical cancer cells." (PMID 27364926, 2016). "However, combined treatment with verteporfin and AG1478 completely blocked the growth of ME180-YAPS127A cells on soft agar, suggesting that the combined targeting of the Hippo/YAP and EGFR pathways may be a more efficient way to inhibit cervical cancer cell growth (Fig8D)." (PMID 26417066, 2015). "We also found that the Hippo signaling pathway, through interaction with the EGFR signaling pathway, regulates progression of cervical cancer via an autocrine loop involving EGF-like ligands, EGFR, and the Hippo pathway." (PMID 26417066, 2015). "TGF-α and amphiregulin (AREG), via EGFR, inhibit the Hippo signaling pathway and activate YAP to induce cervical cancer cell proliferation and migration." (PMID 26417066, 2015). "This suggests that deregulated signaling through EGFR is likely to account, at least in part, for increased expression of COX-2 in cervical cancer." (PMID 24860830, 2014). "Our findings, therefore, identify a novel mechanism that mediates EGF/EGFR-induced EMT and a potential therapeutic target for cervical cancer." (PMID 23936413, 2013). "Chronic EGF treatment induces EMT via up-regulation of EMT-inducing transcription factor Snail in cervical cancer cells, and EGF-mediated EMT is correlated with EGF receptor (EGFR) overexpression and clinical progression of cervical cancer." (PMID 23936413, 2013). "EGF triggers a cascade of signaling events through interaction with its receptor, EGFR, and has been proven to be a potent inducer of EMT in cervical cancer." (PMID 23936413, 2013). "Whereas ICD-antibodies only target whole EGFR and the EGFRvIII mutant, the ECD-antibodies also detect sEGFR like isoforms b, c and d as shown by Halle and coworkers in cervical cancers." (PMID 22623992, 2012). "In cervical cancer, VEGF upregulates EGFR and downregulates IGF-BP3, thus amplifying the cell proliferative activity of EGFR." (PMID 22363346, 2012). "Furthermore, expression of high-risk HPV E6 has been linked to an increase in EGFR levels, and changes in functional levels of the HPV E6/E7 proteins may alter the growth rate of cervical carcinoma cell lines by reducing the stability of EGFR at the posttranscriptional level." (PMID 21730982, 2011). "Human papillomavirus is an aetiologic factor for cervical carcinoma, and HPV proteins seem to play an important role in EGFR expression." (PMID 21730982, 2011). "In cervical cancer patients two molecules are currently investigated as target for MoAbs-specific treatment: VEGF and EGFR." (PMID 22235224, 2011). "The present study is the first to compare the EGFR and HER2 receptor status in primary cervical cancers with their lymph node metastases." (PMID 18700025, 2008). "The aim of this study was to evaluate the EGFR and HER2 receptor expression, using immunohistochemical analyses, in primary cervical cancers and determine if the expression is retained in lymph node metastases." (PMID 18700025, 2008).
cervical carcinoma (continued). "Expression of EGFR and HER2 was investigated immunohistochemically in both lymph node metastases and corresponding primary cervical cancers (n = 53)." (PMID 18700025, 2008). "In the present study, the expression of EGFR and HER2 was investigated immunohistochemically in a series of 53 primary cervical cancers and corresponding lymph node metastases." (PMID 18700025, 2008). "Similarly, Erlotinib, an EGFR-TKI, effectively prevents CSC enrichment in paclitaxel-resistant cervical cancer cells by suppressing IL-6 production." (PMID 41373619, 2025). "Despite the pivotal role of EGFR signaling, current international guidelines (ESGO, NCCN, ASCO, FIGO, ESMO, and others) for recurrent cervical cancer primarily recommend platinum-based chemotherapy, bevacizumab, and immunotherapy, without incorporating EGFR inhibitors." (PMID 41156200, 2025). "In this study, we demonstrated that dihydrocapsaicin (DHC), a major capsaicinoid found in red peppers, enhances tumor necrosis factor-α (TNF-α)-induced G1 cell cycle arrest and apoptosis in HeLa human cervical cancer cells through the suppression of TAK1-mediated NF-κB and EGFR survival pathways." (PMID 40507823, 2025). "EGFR, TNF-α, and VEGFA are the key targets related to the prognosis of cervical cancer." (PMID 40238841, 2025). "Our integrated analysis of databases revealed that MMP-9, EGFR, AKT, and caspase-3 may be the drug targets of naringenin in cervical cancer." (PMID 38253629, 2024). "Additionally, elevated expression of EGFR was promoted by overexpressed AFAP1-AS1, and the function of AFAP1-AS1 on cell development and drug resistance in cervical cancer cells were both reversed by the knockdown of EGFR or overexpression of miR-7-5p." (PMID 39574469, 2024). "MUC1 increased expression after paclitaxel treatment supports acquired chemoresistance via MUC1-C/EGFR complex nuclear activity, thereby EGFR inhibition by Erlonitib sensitized cells to paclitaxel, abrogated CD133 + cells enrichment and prevented disease relapse of cervical cancer." (PMID 37922108, 2024). "Firstly, although the results of the signaling pathways showed that AFAP1-AS1/miR-7-5p/EGFR axis induced the phosphorylation of AKT and MAPK in cervical cancer, the direct role of AKT and MAPK signaling pathway still needs to be confirmed by pharmacological block in the further study." (PMID 39574469, 2024). "It has been reported that the EGFR present in cervical cancer cell lines CALO and INBL has putative mutations in the region αC of the kinase domain, resulting in EGFR being present but not phosphorylated." (PMID 37372319, 2023). "Other studies have reported an absence of a relationship between EGFR overexpression and outcome in cervical cancer." (PMID 38414930, 2023). "To investigate potential targets for impeding NANOG-driven autophagy in cisplatin-resistant tumor cells, we compared the expression of genes involved in EGFR hyperactivation among the genes upregulated by NANOG and highly expressed in chemotherapy-resistant cervical cancer patients." (PMID 37165076, 2023). "Therefore, TN indeed induced degradation of EGFR and PDGFRα and suppressed PI3K/Akt/mTOR cascade in cervical cancer cells." (PMID 39282148, 2022). "(2020) demonstrated that targeting CD109 by siRNA or CRISPR/Cas9 could inhibit cervical cancers’ tumorigenic and aggressive properties by inactivating the CD109/EGFR/STAT3 axis in vitro and in vivo." (PMID 35508982, 2022). "At present, the use of EGFR inhibitors has been investigated in phase II studies in recurrent or metastatic cervical cancer patients and has shown minimal or no benefit at all." (PMID 34830902, 2021). "The addition of media containing a neutralising EGFR antibody failed to rescue colony formation, suggesting that EGFR signalling plays a role in the diminished proliferative ability of JNK-inhibited cervical cancer cells (compare bar 8 with bar 7)." (PMID 33303976, 2021).
cervical carcinoma (continued). "cBioPortal analysis revealed that EGFR, uPA, and TM are positively correlated in tumor samples of cervical cancer patients, showing a negative prognostic impact." (PMID 33886813, 2021). "This understanding of the single molecular pathway, HPV16 E6/miR-2861/EGFR/AKT2/CCND1, may provide a new insight into exploring additional strategies for cervical cancer therapy in the future." (PMID 33803022, 2021). "Our data showing EGFR/ERK signaling to c-Fos, JunB and JunD activation are also consistent with reports that the expression of these AP-1 factors increases substantially in HPV(+) cervical cancers and cancer cell lines." (PMID 33481911, 2021). "The reduced level of E5 in HPV-16-positive cervical cancer cells showed no significant alteration in the EGFR expression level in the test group compared to the control and scrambled siRNA groups." (PMID 37305401, 2021). "TACC3 was previously suggested to piay a vital role in epidermal growth factor (EGF) mediated EMT, which represents a promising therapeutic strategy for the treatment of cervical carcinoma and is involved in the EGF/EGF receptor (EGFR) signal transduction pathway." (PMID 34134633, 2021). "A decrease in autophagy was correlated with the elevated radioresistance of hypoxic colorectal cancer cells and cervical cancer cells in which autophagy was suppressed by MiR-21 via the Akt/mTOR signaling pathway and dependent on the EGF receptor (EGFR) expression." (PMID 33806538, 2021). "Complex 24 (IC50 to EGFR = 29.1 nM) was revealed to be a promising antiproliferative agent against MCF-7 breast (IC50 = 17.3 μM) and HeLa cervical cancer cells (IC50 = 1.4 μM), with selectivity index values (EGFR-induced versus non-induced growth of the cell lines) higher than 6 and 3, respectively." (PMID 34070457, 2021). "During metastasis activation, cervical cancer cells express several genes and proteins, including the homeobox (HOX) gene, PI3K/AKT/mTOR, epidermal growth factor receptor (EGFR), platelet-derived growth factor receptor (PDGFR), vascular endothelial growth factor (VEGF), and vimentin." (PMID 33921245, 2021). "Different clinical trials have been performed employing anti-EGFR therapy for cervical cancer patients, showing ambiguous results: either with no beneficial outcomes, treatment-associated side effects, or an approximate 10% increase in overall survival." (PMID 33886813, 2021). "In cervical cancer, KDM5C represses the expression of the EGFR to function as a tumor suppressor." (PMID 32714863, 2020). "Moreover, we also reported an interplay between the EGFR signaling pathway and components of the LPCAT-PAF-PAFR axis in cervical cancer cells." (PMID 33392068, 2020). "Finally, combined EGFR and PAFR inhibition compromised cell viability and clonogenic capacity of aggressive cervical cancer cells." (PMID 33392068, 2020). "PD153035 and LY294002 respectively inhibit EGFR and PI3K, which could inhibit GALNT7′s promoting effect on the proliferation and invasion of cervical cancer cells." (PMID 32308562, 2020). "In this study, we employed The Cancer Genome Atlas (TCGA) and cancer cell lines to evaluate possible cooperation between EGFR, PAFR, and lysophosphatidylcholine acyltransferases (LPCATs), enzymes involved in the PAF biosynthesis, in the context of cervical cancer." (PMID 33392068, 2020). "To investigate whether CD109 facilitates the EGFR/STAT3 signalling, we performed a Western blot analysis to determine the expression of CD109 and EGFR, and the phosphorylation of STAT3 in different cervical cancer cell lines." (PMID 32507856, 2020). "Indeed, EGFR activation upregulated the expression of PAFR and LPCAT2 in cervical cancer cells through a MAPK-dependent mechanism." (PMID 33392068, 2020). "EGFR activation induces translocation of PKM2 into the nucleus, where PKM2 acts both as a protein kinase and a transcriptional coactivator for hypoxia-inducible factor alpha (HIF-1α) in HeLa cervical carcinoma cells." (PMID 32695675, 2020).
cervical carcinoma (continued). "In addition, a recent study demonstrated a promising effect of lapatinib (anti- EGFR and HER-2), in HER-expressing cervical cancer cells by reducing the number and size of blood vessels and preventing increased HIF-1α levels." (PMID 30760827, 2019). "As KP exhibits the ability to impede the tumorigenic influence of EGFR and IL-6 signaling in HeLa cells, we believe that KP could be a good candidate to be developed as an agent for treating HPV18-positive cervical cancer." (PMID 31470515, 2019). "Moreover, key gene mutations, such as phosphatidylinositide 3-kinases catalytic subunit α (PIK3CA), Kirsten rat sarcoma viral oncogene homolog (KRAS), and epidermal growth factor receptor (EGFR), have been observed in cervical cancer patients." (PMID 31709304, 2019). "Indeed, by using a loss-of-function approach, we confirmed that activation of the EGFR-IL-6 pathway and enrichment of paclitaxel-resistant CSCs depended on MUC1 expression in cervical cancer." (PMID 31772161, 2019). "Studies have shown that abnormal expressions of signaling molecules including phosphatidylinositol 3-kinase (PI3K), epidermal growth factor receptor (EGF-R), β-catenin, extracellular signal-regulated kinase (ERK) and Bcl-2 played significant parts in cervical cancer progression." (PMID 31255182, 2019). "In addition, the increased expression of EGFR, PAR2 or COX2 in cervical cancer patients was significantly correlated with poor overall survival." (PMID 30093972, 2018). "One pathway leading to EGFR signaling that has not been thoroughly investigated in cervical cancer progression involves transactivation by G-protein-coupled receptors, such as PAR2." (PMID 30093972, 2018). "In contrast, other investigators found that EGFR was not an indicator of prognosis for patients with cervical cancer including adenocarcinoma." (PMID 28859123, 2017). "We demonstrate that ATXN1 is overexpressed in cervical cancer cells; this overexpression could have been induced by factors such as EGF and that EGF-mediated ATXN1 induction depends on the activation of the EGFR–RAS–MAPK pathway." (PMID 29212253, 2017). "Although most of the cervical cancer cell lines were EGFR positive and all were RASwt, their EGFR expression levels were relatively low, and, in keeping with clinical observations for cervical cancer, they did not respond to CET as a single agent." (PMID 27783105, 2017). "M2 macrophages are also supposed to have a negative impact on cervical cancer therapy, such as therapy with immunoglobulin G (IgG) antibodies directed against epidermal growth factor receptor (EGFR)." (PMID 28895886, 2017). "Whereas CET monotherapy was ineffective against the panel of cervical cancer cell lines, irrespective of their EGFR expression levels and despite their RASwt status, it significantly enhanced the in vitro cytotoxic efficacy of activated PBNK (P = 0.002)." (PMID 27783105, 2017). "In summary, our data suggest that CD73 overexpression promote cervical cancer cells proliferation and migration, via potentiating EGFR/Akt and VEGF/Akt pathway, independent of its enzymatic activity." (PMID 28202050, 2017). "Besides, tumor growth and angiogenesis in cervical cancer-implanted mice were inhibited by curcumin via down-regulating vascular endothelial growth factor (VEGF), cyclooxygenase-2 (COX-2) and EGFR." (PMID 27529277, 2016).
cervical carcinoma (continued). "Though EGFR, AKT2, and CCND1 are regulated by multiple factors, out data suggest that miR-2861 exhibits tumor suppressor role by suppressing multiple targets including EGFR, AKT2, and CCND1 in HPV16 positive cervical cancer cells." (PMID 27364926, 2016). "Therefore, the present study was designed to determine the effects of THC on tumor growth in cervical cancer- (CaSki-) implanted nude mice and to study the possible mechanisms of THC on EGFR and COX-2 expression and their signaling." (PMID 26881213, 2016). "Several small-scale clinical trials of EGFR inhibitors have been completed in cervical cancer patients, but the effects of these drugs are not yet well established." (PMID 27438047, 2016). "This understanding of unique molecular pathway, HPV16 E6/miR-2861/EGFR/AKT2/CCND1, may provide the novel insight into the exploration of additional strategies for cervical cancer therapy in the future." (PMID 27364926, 2016). "One study that explored the relationship between circulating EGFR levels and cervical cancer was not excluded because it reduced the source of heterogeneity." (PMID 27438047, 2016). "Furthermore, we identified a new pathway employing miR-2861, EGFR, AKT2, and CCND1 that mediates HPV16 E6 induced initiation and progression of cervical cancer." (PMID 27364926, 2016). "Stress conditions induced endocytosis and degradation of EGFR independent of ligand stimulation in cervical cancer HeLa cells." (PMID 27034618, 2016). "Furthermore, blocking EGFR activity with AG1478, or knockdown of EGFR using siEGFR, eliminated YAP-induced cell proliferation and AREG secretion of cervical cancer cells." (PMID 26417066, 2015). "This evidence clearly suggests that in cervical cancer cells, the TGF-α/EGFR pathway interacts with the Hippo/YAP signaling pathway to form an autocrine/paracrine loop, which may play critical role in regulating cervical cancer progression." (PMID 26417066, 2015). "Therefore, the present study was designed to determine the effects of CUR on angiogenesis and tumor progression in cervical cancer- (CaSki-) implanted nude mice and to study the possible mechanisms of CUR on angiogenic biomarkers, VEGF, COX-2, and EGFR." (PMID 24860830, 2014). "Therefore, EGFR-COX-2-PGE2 pathway also plays an important role in tumor growth and angiogenesis in cervical cancer." (PMID 24860830, 2014). "Unfortunately, EGFR inhibitor monotherapy was not efficient in patients with recurring locoregionally advanced or metastatic cervical cancer." (PMID 23936413, 2013). "Dual targeting of EGFR and angiogenesis pathways was not synergistic in early trials of cervical cancers, but the population was too small and the tolerance of full dose for either pathway inhibition was not satisfactory to draw valid conclusions." (PMID 22091418, 2011). "The prediction of a response to EGFR targeted therapy in cervical cancer remains a matter of debate since no precise molecular studies are available." (PMID 22091418, 2011). "The literature was reviewed for similar investigations, but no other studies comparing primary cervical cancers and their corresponding metastases regarding EGFR and HER2 were found by the authors." (PMID 18700025, 2008). "Following qualification of targets in this cancer-related pathway, a functional cellular assay was used to analyze the potential therapeutic benefit of combining RNAi and kinase inhibitors against EGFR and MEK-1 in the AP-1 activation pathway of a human cervical cancer cell line." (PMID 16202132, 2005). "Given the critical roles of TAK1, NF-κB, and EGFR signaling in promoting tumor cell survival and therapy resistance, a deeper understanding of how DHC modulates these pathways could reveal novel strategies for cervical cancer treatment." (PMID 40507823, 2025). "While EGFR overexpression is common in cervical cancer, not all patients may have tumours that are dependent on EGFR signalling." (PMID 37310466, 2023).